SNHG7 (small nucleolar RNA host gene 7)
Diseases named in the same sentence as SNHG7 in open-access papers (continued):
Sharing a sentence is not in itself a finding about the gene and the disease.
hepatocellular carcinoma (9 papers, 2019 to 2024). A malignant tumor that arises from hepatocytes. "Overall, these findings elucidated that the overexpressed SNHG7 may be associated with progression, metastasis, and poor prognosis of patients with hepatic carcinoma." (PMID 31478234, 2019). "In addition, overexpressed SNHG7 in hepatic carcinoma patients was significantly associated with aggressiveness, OS rate, and clinical stage." (PMID 31478234, 2019). "The change of SNHG7 is verified as a predictive tool in several disorders, such as neonatal sepsis, hepatocellular carcinoma, and colon adenocarcinoma." (PMID 39014478, 2024). "The expression level of lncRNA small nucleolar RNA host gene 7 (SNHG7) was higher in hepatocellular carcinoma (HCC) tissues and liver cancer cells than adjacent normal tissues and normal liver epithelial cells." (PMID 36387211, 2022). "Further, Kaplan‐Meier survival analysis also showed that up‐regulated SNHG7 was positive correlation with poor OS of patients with hepatic carcinoma." (PMID 31478234, 2019). "Together, our study elucidated the role of SNHG7 as a ceRNA in hepatic carcinoma, provided new potential diagnosis and therapeutic application in hepatic carcinoma progression." (PMID 31478234, 2019). "The result suggested that SNHG7 was significantly overexpressed in hepatic carcinoma tissue compared with adjacent normal tissue." (PMID 31478234, 2019). "In present study, we first revealed that SNHG7 overexpression is a characteristic molecular change in hepatic carcinoma progression." (PMID 31478234, 2019). "Knockdown experiments identified the oncogenous function of SNHG7 in promoting cellular proliferation and metastasis, suppressing apoptosis in hepatic carcinoma." (PMID 31478234, 2019). "Moreover, the SNHG7 expression level may be associated with the metastasis of hepatic carcinoma." (PMID 31478234, 2019). "In the present study, we found that SNHG7 expression was significantly upregulated in hepatic carcinoma tissues, especially in aggressive cases, and it was closely correlated with the poor prognosis." (PMID 31478234, 2019). "Above results suggested that SNHG7 promotes metastasis of hepatic carcinoma cell via Wnt/β‐catenin/EMT signalling pathway as a miR‐425 sponge." (PMID 31478234, 2019). "In‐depth mechanism research revealed that SNHG7 acts as a ceRNA for hsa‐miR‐425‐5p (miR‐425), which sponged miR‐425 and regulated the Wnt/β‐catenin signalling pathway in hepatic carcinoma." (PMID 31478234, 2019). "Meanwhile, immunohistochemical assay illuminated knockdown of SNHG7 promoted cell apoptosis in tumour tissues, as well as suppressed metastasis of hepatic carcinoma." (PMID 31478234, 2019). "Similarly, lncRNA small nucleolar host gene 7 (SNHG7) expression was increased in hepatocellular carcinoma (HCC)." (PMID 36059539, 2022). "RNA interference was performed to explore the biologic function of SNHG7 in hepatic carcinoma." (PMID 31478234, 2019). "Collectively, above findings were according with our results in vitro; knockdown of SNHG7 could impede hepatic carcinoma cell proliferation in nude mice." (PMID 31478234, 2019). "Collectively, our data elucidated the crucial role of SNHG7 in hepatic carcinoma progression." (PMID 31478234, 2019). "Above result suggested that knockdown of SNHG7 could impede hepatic carcinoma cell proliferation and metastasis." (PMID 31478234, 2019). "Collectively, SNHG7 could promoted proliferation and metastasis of hepatic carcinoma cell in vitro and in vivo, suggesting that SNHG7 exert tumorigenic role in hepatic carcinoma progression." (PMID 31478234, 2019). "SNHG7 could promote proliferation and metastasis of hepatic carcinoma cell in vitro and in vivo, suggesting that SNHG7 exerts tumorigenic role in hepatic carcinoma progression." (PMID 31478234, 2019). "Furthermore, knockdown of SNHG7 inhibited the proliferation, migration, and invasion of hepatic carcinoma cell lines in vitro." (PMID 31478234, 2019).
hepatocellular carcinoma (continued). "For instance, several studies assess the role of SNHG7 knockdown on hepatocellular carcinoma (HCC) growth in xenograft mice." (PMID 35111760, 2021). "Therefore, the SNHG7/miR‐425 axis might be a potential therapeutic target for hepatic carcinoma treatment." (PMID 31478234, 2019). "SNHG7 regulated Wnt/β‐catenin/EMT pathway through sponging miR‐425 and played an oncogenic role in hepatic carcinoma progression." (PMID 31478234, 2019). "However, the function of SNHG7 in hepatic carcinoma remains unclear." (PMID 31478234, 2019).
pancreatic cancer (9 papers, 2019 to 2024). "In pancreatic cancer, SNHG7 is highly expressed, and the knockdown of this gene inhibits tumor progression through the miR-342-3p/ID4 axis." (PMID 39195675, 2024). "There is also enough evidence to demonstrate that MSCs increase SNHG7 expression in pancreatic cancer cells, followed by promoting the folfirinox resistance." (PMID 35572560, 2022). "Previous research has found that SNHG7 is overexpressed in pancreatic cancer tissues and promotes metabolic plasticity via antioxidant synthesis." (PMID 34631547, 2021). "SNHG7 overexpression decreased cell apoptosis, and Folfirinox-induced apoptosis was reversed by SNHG7 ectopic expression in pancreatic cancer cells." (PMID 34631547, 2021). "MSC co-culture increased SNHG7 expression in pancreatic cancer cells, contributing to the stemness and Folfirinox resistance." (PMID 34631547, 2021). "SNHG7 was shown to be increased in pancreatic cancer tissues as compared to normal tissues (n = 50)." (PMID 34631547, 2021). "In conclusion, our findings show that MSCs increased SNHG7 expression in pancreatic cancer cells, promoting the stemness and Folfirinox resistance via the Notch1/Jagged1/Hes-1 signaling pathway." (PMID 34631547, 2021). "We found that the overexpression of SNHG7 confers Folfirinox resistance and enhances the stemness of pancreatic cancer cells." (PMID 34631547, 2021). "SNHG7 promotes the proliferation of pancreatic cancer cells through ID4 by competitively binding miR‐342‐3p." (PMID 32892482, 2020). "MSCs could increase the expression of SNHG7 in pancreatic cancer cells, which would promote the dryness and Folfirinox resistance of pancreatic cancer cells through the Notch1/Jagged1/Hes-1 signaling pathway." (PMID 35281017, 2022). "The key finding of this study is that SNHG7 plays a significant role in pancreatic cancer." (PMID 34631547, 2021). "Hence, our findings indicated that SNHG7 interacted with Notch1 to regulate the stemness and Folfirinox resistance in pancreatic cancer." (PMID 34631547, 2021). "In this study, we looked at the unique biological effects of SNHG7 in pancreatic cancer." (PMID 34631547, 2021). "Our result not only helps us to better understand the regulatory potential of SNHG7 in pancreatic cancer stemness and Folfirinox resistance, but it is also important for identifying new pharmacological targets and devising innovative treatment techniques to overcome resistance." (PMID 34631547, 2021). "Finally, our findings showed that MSCs increased SNHG7 expression in pancreatic cancer cells, promoting the stemness and Folfirinox resistance via the Notch1/Jagged1/Hes-1 signaling pathway." (PMID 34631547, 2021). "Therefore, we deduced that Notch1 was a target for SNHG7 in pancreatic cancer." (PMID 34631547, 2021). "We found that the expression of SNHG7 was obviously increased both in pancreatic cancer after the co-culture with MSCs when compared to non-cultured cells." (PMID 34631547, 2021). "We found that SNHG7 expression was higher in pancreatic cancer tissues that were both CD29 and CD90 positive (CD29+CD90+) than in pancreatic cancer tissues that were both CD29 and CD90 negative (CD29CD90)." (PMID 34631547, 2021).
prostate carcinoma (9 papers, 2019 to 2025). A carcinoma that arises from epithelial cells of the prostate gland. "It has been established that the small nuclear kernel RNA host gene 7 (SNHG7) has an oncogenic function in prostate cancer." (PMID 40129567, 2025). "SNHG7 contributes to the development of prostate cancer by promoting glycolysis via the SRSF1/c-Myc axis in two prostate cancer cell lines, PC-3 and DU-145." (PMID 40129567, 2025). "On a mechanical level, in prostate cancer PC-3 and DU-145 cells, SNHG7 stimulated glycolysis via the SRSF1/c-MYC axis; N6-methyladenosine (m6A) modification by methyltransferase-like 3 (METTL3) boosted SNHG7 stability." (PMID 39346921, 2024). "Additionally, in prostate cancer,SNHG7 promotes cell proliferation via cyclin D1 by modulatingmiR-503.Further, SNHG7 sponges miR-34a and induces over-expression ofGALNT7, which in turn results in the progression of colo-rectalcancer." (PMID 32453338, 2020). "In addition to NORAD, the small nucleolar RNA host gene 7 (SNHG7) and lncRNA SOX2 overlapping transcript (SOX2-OT) are identified as EMT-related lncRNAs that are involved in prostate cancer progression and metastasis." (PMID 36483915, 2022).
ovarian carcinoma (7 papers, 2020 to 2025). A malignant neoplasm originating from the surface ovarian epithelium. "This study investigated the expression profiles of seven specific long noncoding RNAs (lncRNAs)—SNHG7, TUG1, XIST1, PRLB, TLR8-AS1, ZFAS1, and PVT1—associated with epithelial ovarian cancer and their relationship with drug resistance." (PMID 39992529, 2025). "Metformin can enhance paclitaxel sensitivity by regulating the expression levels of lncRNA small nucleolar RNA host gene 7 (SNHG7) and miR-3127-5p and impeding the autophagy process in animal models of ovarian cancer and cancer cells." (PMID 33849540, 2021). "Recently, there has been a progressive discovery in the investigation of small nucleolar RNA host gene 7 (SNGH7) in ovarian cancer." (PMID 34631547, 2021). "Our study revealed that the taken together, our results indicate that SNHG7 is significantly up‐regulated in ovarian cancer tissues." (PMID 32420685, 2020). "Among lncRNAs, we found SNHG3 and SNHG7 to be enriched in ovarian cancer stem cell exosomes." (PMID 39891297, 2025). "Metformin inhibits the viability of paclitaxel ovarian cancer cells, increases the expression of SNHG7, and promotes autophagy in ovarian cancer cells; Metformin enhances the sensitivity of ovarian cancer cells to paclitaxel by regulating the SNHG7/miR-3127-5p axis to mediate autophagy." (PMID 38481525, 2024). "Small nucleolar RNA host gene 7 (SNHG7) has been shown to be carcinogenic in ovarian cancer." (PMID 34631547, 2021). "Similarly, we found lncRNAs, including Small Nucleolar RNA Host Gene 3 (SNHG3) and Small Nucleolar RNA Host Gene 7 (SNHG7), to be enriched in ovarian cancer stem cell exosomes, highlighting a potential role in stem cell-like properties and tumor aggressiveness." (PMID 39891297, 2025).
thyroid cancer (7 papers, 2020 to 2025). "Existing studies shown that upregulation of ACSL1 is regulated by SNHG7/ miR-449a to cause proliferation and migration of thyroid cancer cells." (PMID 37596597, 2023). "Small nuclear RNA host gene 7 (SNHG7) is highly expressed in gastric and thyroid cancer and is associated with tumor stage and overall survival." (PMID 35992788, 2022). "Multiple studies have confirmed that SNHG7 is significantly overexpressed in thyroid cancer tissues and cell lines, with its upregulation closely associated with increased tumor diameter, TNM staging, and poor patient prognosis." (PMID 41234719, 2025). "In summary, SNHG7 promotes the malignant phenotype of thyroid cancer cells through multiple miRNA-related regulatory pathways and contributes to the development of radioactive iodine tolerance." (PMID 41234719, 2025). "Functional experiments further indicate that silencing SNHG7 significantly inhibits proliferation, migration, and invasion of thyroid cancer cells while promoting apoptosis, suggesting its pivotal role in thyroid cancer development." (PMID 41234719, 2025). "Based on TCGA data analysis, we found that SNHG7 was upregulated in 17 of the 33 cancer types investigated, including cholangiocarcinoma (CHOL), prostate adenocarcinoma (PRAD), and thyroid carcinoma (THCA)." (PMID 35747807, 2022). "The high expression levels of SNHG7 are correlated with advanced stages (III and IV) and shorter survival times in of thyroid cancer patients." (PMID 32760219, 2020). "In thyroid carcinoma, certain SNHG family members (e.g., SNHG7, SNHG15, SNHG12, SNHG14) have been reported as oncogenes, while others (e.g., SNHG3, SNHG5) may function as tumor suppressors—a discrepancy warranting further investigation." (PMID 41234719, 2025).
lymph node metastasis (6 papers, 2021 to 2022). "The expression of SNHG7 also significantly positively correlated with the tumor stage and lymph node metastasis in COAD." (PMID 35646635, 2022). "Several studies have shown that the high-level expression of SNHG7 correlates with lymph node metastasis, distant metastasis, and tumor invasion depth in various tumors." (PMID 36185210, 2022). "High expression of SNHG7 was associated with TNM stage, depth of invasion, lymph-node metastasis, and distant metastasis." (PMID 33842553, 2021). "Furthermore, elevated SNHG7 expression significantly predicted lymph node metastasis (LNM) (HR = 1.98, 95% CI: 1.74–2.26, p <0.001) and distant metastasis (DM) (HR = 2.49, 95% CI: 1.88–3.30, p<0.001) respectively." (PMID 34979987, 2022). "Additionally, elevated SNHG7 expression was correlated with TNM stage (OR: 3.31, 95%CI = 2.29–4.80, P = 0.000), lymph node metastasis (OR = 3.32, 95%CI = 1.61–6.83, P = 0.004), and tumor differentiation (OR = 1.92, 95%CI = 1.22–3.03, P =0.005) in patients with cancers." (PMID 34714775, 2021).
colon adenocarcinoma (5 papers, 2018 to 2024). "Interestingly, from TCGA database, we also found that SNHG7 was associated with overall survival of colon adenocarcinoma (COAD) patients." (PMID 29915311, 2018). "SNHG7 overexpression was identified in cholangiocarcinoma (CHOL), colon adenocarcinoma (COAD), liver hepatocellular carcinoma (LIHC), pheochromocytoma and paraganglioma (PCPG) (|Log2fold change (FC)| cutoff >1 and P<0.01)." (PMID 34714775, 2021).
colon cancer (5 papers, 2019 to 2024). "SNHG7 has also been implicated in developing drug resistance in COAD, such as promoting anlotinib resistance in colon cancer." (PMID 39115621, 2024). "LncRNA small nucleolar RNA host gene 7 (SNHG7) is overexpressed in colon advanced adenomas and early-stage colon cancer, and SNHG7 downregulation in HT29 cells retards cell proliferation via interacting with miR-193b and suppressing K-ras/ERK/cyclin D1." (PMID 33246471, 2020). "We utilized qRT-PCR to confirm the findings and found that AP003555.1, AL683813.1, SNHG7, ZEB1-AS1, AC074212.1 and RPL37A-DT were considerably overexpressed in human colon cancer cell lines (SW480, SW620, LOVO) compared to normal intestinal epithelial cell (FHC)." (PMID 37946148, 2023). "Additionally, GALNT1 was the direct target gene of MIR216B, and SNHG7 could act as a ceRNA to sponge MIR216B, and rescue GALNT1 to facilitate colon cancer cell invasion." (PMID 31691514, 2019).
neuroblastoma (5 papers, 2019 to 2025). Neuroblastoma (NB) is the most common solid, extracranial childhood tumor. "Small nucleolar RNA host gene-7 (SNHG7) is a lncRNA that is upregulated in neuroblastoma, where it plays a significant role in cell proliferation and is associated with poor prognosis." (PMID 40104501, 2025). "SNHG7 expression is increased in granulin (GRN) peptide treated human neuroblastoma cells." (PMID 31836762, 2019). "As well as that, NORAD, SNHG7, and SNHG16 have been shown to be involved in conferring this phenotype in neuroblastoma." (PMID 34178658, 2021).
atherosclerosis (4 papers, 2021 to 2024). A disease characterized by the build-up of fatty material and calcium deposition in the arterial wall resulting in partial or complete occlusion of the arterial lumen. "The upregulation of SNHG7 in atherosclerosis was consistent with our findings." (PMID 39014478, 2024). "A recent publication suggested that SNHG7 provides protection against atherosclerosis development, suggesting that patients with COVID-19 are more likely to develop atherosclerosis or more severe atherosclerosis." (PMID 37109540, 2023).
cervical cancer (4 papers, 2020 to 2024). A primary or metastatic malignant neoplasm involving the cervix. "SNHG7 facilitated cell proliferation and invasion and closely related to poor prognosis in cervical cancer." (PMID 34512753, 2021). "Many lncRNAs have been shown to participate in the occurrence and progression of cervical cancer, either promoting (like SNHG7) or inhibiting (like GAS5) the disease." (PMID 33328990, 2020).
glioma (4 papers, 2020 to 2025). A benign or malignant brain and spinal cord tumor that arises from glial cells (astrocytes, oligodendrocytes, ependymal cells). "Significantly decreased levels of LINC00205, FGD5-AS1, and SNHG7 were characteristic for high-grade gliomas as compared to lower-grade tumours, while SNHG3 showed opposite associations." (PMID 36597408, 2023). "Rescue experiments indicated that CTNNB1 overexpression abolished the inhibitory effects of SNHG7 inhibition on glioma progression." (PMID 32009853, 2020). "SNHG7 may enhance the proliferation of glioma by regulating the miR-138-5p/EZH2 signal axis." (PMID 35127343, 2022).
liver fibrosis (4 papers, 2020 to 2026). "I, similarly SNHG7 inhibition was associated with reduced survival and proliferation rates in liver fibrosis mice." (PMID 34899344, 2021). "In conclusion, all these data suggest that SNHG7 is an impressive possible therapeutic target and a potential diagnostic marker for liver fibrosis." (PMID 34899344, 2021). "Loss of SNHG7 induced the inhibition of mouse HSC activation and liver fibrosis in vivo, whereas miR-378a-3p downregulation blocked the effects of SNHG7 loss on mouse HSC activation." (PMID 32098245, 2020). "Understanding the SNHG7 functional mechanism in mouse HSCs is important for the analysis of liver fibrosis progression." (PMID 32098245, 2020). "These discoveries suggest that lncRNA SNHG7 may interact with different miRNAs to play a critical role in the development of liver fibrosis." (PMID 34899344, 2021). "lncRNA SNHG7 is higher in the cytoplasm of human LX-2 cells as well as primary HSC than in the nucleus, and this evidence indicates that the expression of lincRNA-p21 and lncRNA SNHG7 plays a key role in the progression of liver fibrosis and its potential as a potential biomarker of liver fibrosis." (PMID 34899344, 2021).
cholangiocarcinoma (3 papers, 2021 to 2022). A carcinoma that arises from the intrahepatic biliary tree (intrahepatic cholangiocarcinoma) or from the junction, or adjacent to the junction, of the right and left hepatic ducts (hilar cholangiocarcinoma). "In terms of SNHG7 dysregulation, SNHG7 overexpression was identified in Cholangiocarcinoma (CHOL), Lymphoid Neoplasm Diffuse Large B-cell Lymphoma (DLBC), Pheochromocytoma and Paraganglioma (PCPG), and thymoma (THYM)." (PMID 34979987, 2022).
non-small cell lung carcinoma (3 papers, 2021 to 2023). A group of at least three distinct histological types of lung cancer, including non-small cell squamous cell carcinoma, adenocarcinoma, and large cell carcinoma. "Additionally, our results revealed that SNHG7 and E2F7 were upregulated, while miR-181a-5p is underexpressed in non-small-cell lung cancer." (PMID 35383161, 2022).